MMP7 (matrix metallopeptidase 7)
Diseases named in the same sentence as MMP7 in open-access papers (continued):
Sharing a sentence is not in itself a finding about the gene and the disease.
gastric cancer (continued). "Surprisingly, MMP7 showed higher staining scores in the tumor center, but it must be taken into account that we scored only positive staining within the gastric cancer cells and not of stromal components which can also express MMP7." (PMID 26652716, 2015). "In the present study with a small cohort of patients, we observed a higher expression of p-mTOR, pS6, p4EBP1, PTEN, and MMP7 proteins in primary gastric cancer tissues than in matched noncancerous tissues." (PMID 25909163, 2015). "To figure out the possible mechanisms of how IGFBP3 regulate the invasiveness of gastric cancer cells, we examined the mRNA levels of MMP2/MMP7/MMP9/MMP14, TIMP1/TIMP2, uPA and its receptor uPAR, all of which are invasion-related factors, especially in gastric cancer." (PMID 24386080, 2013). "Since previous studies reveal the critical roles of MMP-7, MMP-9 and MMP-14 in the invasion and metastasis of gastric cancer, we hypothesized that MJ might influence the expression of these genes." (PMID 23394613, 2013). "A positive correlation of MMP-7 level with the tumor invasion of the gastric wall, lymph node metastasis, peritoneal dissemination and survival of gastric cancer patients has been documented in several studies." (PMID 20939893, 2010). "As negative regulators in Wnt signaling, Secreted Frizzled-Related Proteins (SFRPs) are downregulated in a series of human cancers; and specifically, some matrix metalloproteinases (MMPs), including MMP-2, MMP-7, MMP-9 and MT1-MMP, are frequently overexpressed in gastric cancer." (PMID 19586554, 2009). "Therefore, we tested the changes of MMP-2, MMP-7 and MMP-9 after Grhl2 overexpression in both SGC7901 and MKN45, so as to preliminarily clear the possible mechanisms by which Grhl2 inhibits invasion and migration of gastric cancer." (PMID 28067907, 2017). "While the data presented here is focused on human circulating B-lymphocytes our conclusions are supported by studies in gastric cancer where MMP-7 and MMP-2 expression did not correlate with mTOR activation and Rapamycin failed to decrease MMP-7 secretion despite decreasing mTOR phosphorylation." (PMID 28634370, 2017). "In an additional proof-of-principle approach, we measured the expression of MMP2, MMP7 and MMP9 in MKN45 gastric cancer cells before and after treatment with the mTOR inhibitor rapamycin to investigate the putative link between mTOR signalling and MMP expression in gastric cancer." (PMID 26652716, 2015). "This study aimed to explore whether expression of MMP-7 and TIMP-1 alone and in combination can be used as a prognostic marker for gastric cancer (GC)." (PMID 33005257, 2020). "Our results showed that although expression of MMP-7 or TIMP-1 alone may not serve as an indicator for patient prognosis, there was a significant association between concomitant positive expression of MMP-7 and TIMP-1 with poor survival of patients with gastric carcinoma." (PMID 33005257, 2020). "Our results showed that HOXC-AS3 could bind to YBX1, thus transcriptionally regulating a large set of genes that are linked to cell proliferation and cell migration in gastric cancer cells, such as MMP7, WNT10B, and HDAC5, thus promoting GC cell proliferation and migration." (PMID 30286788, 2018). "In the present study, Grhl2 reduces MMP-2, MMP-7 and MMP-9 expression, which is partly explained by the mechanism by which Grhl2 inhibits gastric cancer cell invasion and migration, but this is obviously not enough." (PMID 28067907, 2017). "Here we showed that pAMPKα and PTEN were down-regulated and p-mTOR, p-S6, p-4EBP1, MMP7, and DCN1 were up-regulated in human gastric cancer tissue samples as compared to that in the noncancerous tissues." (PMID 25909163, 2015). "MMP2, MMP7 and MMP9 have been most extensively investigated in gastric cancer, but never previously in a direct comparison and in association with mTOR expression." (PMID 26652716, 2015).
gastric cancer (continued). "Real-time quantitative RT-PCR revealed the decreased transcript levels of MMP-14, but not of MMP-7 or MMP-9, in gastric cancer cells treated with sub-cytotoxic MJ." (PMID 23394613, 2013). "Western blot indicated that administration of sub-cytotoxic (0.1 and 0.2 mM) MJ resulted in a decrease in the expression of MMP-14, but not of MMP-7 or MMP-9, in cultured gastric cancer SGC-7901 and MKN-45 cells." (PMID 23394613, 2013). "In this study, we found that sub-cytotoxic MJ selectively down-regulated the expression of MMP-14, but not of MMP-7 and MMP-9, in gastric cancer cells." (PMID 23394613, 2013). "The value of MMP-2 as an independent prognostic marker for gastric carcinomas is underscored by our observation that MMP-9, MMP-7, MMP-8, TIMP-1 and TIMP-2 have no prognostic relevance." (PMID 16538217, 2006). "We showed that isoproterenol-induced MMP-7 promoter activation was not disrupted by the mutagenesis of the core-sequences of all three STAT3 sites, suggesting that the STAT3 elements may not act in isoproterenol-induced MMP-7 gene transcription in gastric cancer cells." (PMID 20939893, 2010).
pulmonary fibrosis (90 papers, 2004 to 2026). Chronic progressive interstitial lung disorder characterized by the replacement of the lung tissue by connective tissue, leading to progressive dyspnea, respiratory failure, or right heart failure. "Elevated MMP7 expression is a hallmark of idiopathic pulmonary fibrosis and other interstitial lung diseases, where it has emerged as a candidate biomarker for disease progression." (PMID 41768291, 2026). "While initially considered to be essential to promote re-growth of the ciliated epithelium of the airway, it is now appreciated that sustained activation of MMP7 underlies the pathobiology of pulmonary fibrosis." (PMID 32485920, 2020). "It has been postulated that MMP7 plays a profibrotic role based on the finding that MMP7 deficient mice are protected from bleomycin induced lung fibrosis." (PMID 26944412, 2016). "Allele-specific transactivation of the MMP7 gene by the FOXA2 transcription factor was observed in idiopathic pulmonary fibrosis patients." (PMID 25658610, 2015). "MMP-7 activity has also been previously implicated in the pathogenesis of aberrant lung remodeling in pulmonary fibrosis." (PMID 24136296, 2014). "Strikingly, MMP-7, whose expression has been found up-regulated in idiopathic pulmonary fibrosis as well as in biliary atresia-associated liver fibrosis, was the most up-regulated gene in MHN." (PMID 23185381, 2012). "MMP7 is implicated in the pathogenesis of pulmonary fibrosis in human and animal studies." (PMID 39919729, 2025). "MMP7 is a metalloprotease that has been implicated in the pathogenesis of pulmonary fibrosis." (PMID 37029417, 2023). "The mechanism by which MMP7 may lead to loss of epithelial integrity and eventual lung fibrosis is currently under investigation, and the Atp8b1 mouse model will provide the background on which to explore this mechanism." (PMID 35204783, 2022). "Mice that are MMP‐7 deficient are protected from bleomycin‐induced lung fibrosis." (PMID 33274549, 2021). "Overespression of MMPs was correlated with a more aggressive phenotype of cancer; the overexpression of MMP-7 is associated with tumor proliferation and a poor prognosis in some pulmonary disorders such as non-small cell lung carcinoma and idiopathic pulmonary fibrosis." (PMID 33981713, 2021). "In light of this, it is interesting to note that esomeprazole regulated the gene expression and plasma levels of MMP7 since clinical studies have shown that elevated level of MMP7 (Matrilysin) is associated with increased lung fibrosis and independently predicts survival in IPF." (PMID 26231702, 2015). "MMP‐7‐deficient mice are protected from bleomycin‐induced pulmonary fibrosis." (PMID 25214520, 2014). "MMP-7 activity has been previously reported in association with fibrotic changes in the kidney and other fibrotic conditions, such as idiopathic pulmonary fibrosis and liver fibrosis." (PMID 24273653, 2013). "However, the excessive production of MMP-7 has been clearly associated with the tissue fibrotic response since the MMP7 null mouse is protected from bleomycin-induced lung fibrosis." (PMID 23259796, 2012). "However, other investigators have reported protection from bleomycin-induced pulmonary fibrosis in Mmp7 deficient mice." (PMID 21935365, 2011). "In fact, Mmp7 deficient mice are protected from intratracheal bleomycin-induced pulmonary fibrosis." (PMID 21935365, 2011). "The proteolytic activity of MMP-7 in lung fibrosis, together with its elevated plasma levels in IPF patients, suggests its utility as a biomarker for discriminating between healthy and diseased individuals." (PMID 41301749, 2025). "The expression of MMP-7 was elevated in both human idiopathic pulmonary fibrosis (IPF) and mouse fibrosis models." (PMID 40722657, 2025). "The metalloproteinases MMP-1 (Matrix Metalloproteinase-1) and MMP-7 (Matrix Metalloproteinase-7) are defined as potential peripheral blood biomarkers in idiopathic pulmonary fibrosis (IPF)." (PMID 40733571, 2025).
pulmonary fibrosis (continued). "MMP-7 exerts a significant role in the development of pulmonary fibrosis, including inflammation occurrence, extracellular matrix degradation, abnormal matrix repair, epithelial–mesenchymal transition, as well as tissue remodeling." (PMID 40722657, 2025). "In the present study, we demonstrated that MMP-7 mediated collagen-I synthesis and was involved in the occurrence of ILD; inhibition of MMP-7 prevented pulmonary fibrosis in RA-ILD models." (PMID 40722657, 2025). "The MMP7 gene, serving as a biomarker for pulmonary fibrosis, has been demonstrated to contribute to the development of lung fibrosis through its elevated expression." (PMID 38575860, 2024). "Closely related with MMP-7 is osteopontin (OPN), a secreted pleiotropic glycoprotein that in lungs with idiopathic pulmonary fibrosis colocalises with MMP-7 in alveolar epithelial cells." (PMID 39624381, 2024). "The added value and robustness of the novel functional readouts DLCO and FVC were finally assessed comparing the results obtained with the BALF levels of MMP-7, a prognostic biomarker of lung fibrosis in clinical studies." (PMID 38099140, 2023). "In pulmonary fibrosis, fibrosis-related factors such as chemokines (IL-8, CCL18), proteases (MMP-1, MMP-7) or growth factors have been suggested to have diagnostic potential for fibrosis, but their utility in clinical routine has not been established." (PMID 37814303, 2023). "TNF-α, TGF-β1, IL-6, MCP-1, and MMP-7 are inflammatory mediators and profibrotic factors involved in lung tissue damage and play a significant role in the initiation and progression of pulmonary fibrosis." (PMID 37047142, 2023). "MMP7 has furthermore been highlighted for its function as a plasma biomarker in idiopathic pulmonary fibrosis, in line with its detection in our study." (PMID 37266432, 2023). "Some MMPs (MMP-3 and MMP-7) have been reported to induce EMT in lung fibrosis; however, the role of MMP-2 in EMT is unclear." (PMID 37047672, 2023). "As shown here, MMP7 is upregulated at both the transcript and protein levels in the Atp8b1 mutant mouse, which develops pulmonary fibrosis, a phenotype accelerated by hyperoxia." (PMID 35204783, 2022). "In idiopathic pulmonary fibrosis and connective tissue disease related ILD, biomarkers such as surfactant protein D (SP-D), Club Cell protein 16 (CC16), and matrix metalloproteinase 7 (MMP-7) have been shown to work as diagnostic and prognostic biomarkers." (PMID 35789314, 2022). "Given the emerging links between MMP7 and pulmonary fibrosis in humans, we investigate MMP7 levels in the Atp8b1 mouse lung." (PMID 35204783, 2022). "The change in ciliated cell morphology and apical changes in club cells observed on TEM prompted exploration of the role of ciliogenesis in pulmonary fibrosis, with a specific focus on MMP7." (PMID 35204783, 2022). "Biomarkers related to pulmonary fibrosis such as KL-6, SP-D, MMP-7, IL-6 have a great predictive potential in early diagnosis and treatment responsiveness in patients with post-COVID-19 pulmonary fibrosis." (PMID 35371880, 2022). "Of note, expression of MMP7 was elevated along with spontaneous lung fibrosis in a Sftpc mutant expressing mouse model." (PMID 34728556, 2022). "MMP7 was increased in SSc patients with considerably higher levels of observable lung fibrosis compared to healthy individuals." (PMID 34512395, 2021). "Both MMP3 and MMP7 appear critical to the development of experimental lung fibrosis, with rodents genetically deficient in MMP3 or MMP7 demonstrating a reduction in pulmonary fibrosis after bleomycin challenge." (PMID 32171287, 2020). "The role of MMP-7 has also been thoroughly investigated in idiopathic pulmonary fibrosis (IPF), a rapid progressing fibrotic lung disease affecting the alveolar epithelial cells (AEC)." (PMID 33409288, 2020). "Nevertheless, the multifaceted role of MMP-7 in pulmonary fibrosis and fibroblast survival via sFasL still requires further study." (PMID 32053892, 2020).
pulmonary fibrosis (continued). "Subsequently, we describe how MMP-7 is involved in other pathologies, such as renal and pulmonary fibrosis." (PMID 33409288, 2020). "Consistent with the findings in the kidney, MMP-7 also affects liver and lung fibrosis after a chronic injury." (PMID 32630493, 2020). "When we interrogated the function of these genes further, we found that many of them (e.g., MMP7, GDF15, and MUC5B) have been implicated in the pathogenesis of pulmonary fibrosis." (PMID 33082228, 2020). "Consistently, MMP-7-induced cleavage of the membrane-bound FasL also plays a role in the process of pulmonary fibrosis." (PMID 32630493, 2020). "This supports the understanding of the role of MMPs, and MMP-7 in particular, in pulmonary fibrosis as extending beyond functions such as extracellular matrix remodeling." (PMID 32053892, 2020). "MMP-7 playsa crucial role in a diverse array of cellular processes and appears to be a key regulator of fibrosis in several diseases, including pulmonary fibrosis, liver fibrosis, and cystic fibrosis." (PMID 28239354, 2017). "MMP-7 is expressed at very low levels in adults and in only a few tissues but is upregulated in a variety of disease states, including cancer and idiopathic pulmonary fibrosis." (PMID 28239354, 2017). "A significant association was also retrieved between the -181AA genotype and higher plasmatic levels of MMP7 among idiopathic pulmonary fibrosis patients." (PMID 29317790, 2017). "Elevated serum MMP-7 concentrations are correlated with severe lung fibrosis and poorer survival in patients with IPF." (PMID 29149883, 2017). "MMP7 has been reported as a promising biomarker in various malignancies, including liver cancer, and pulmonary fibrosis, and an automated assay suitable for routine clinical use has recently been developed." (PMID 27861569, 2016). "We also see a link between diagnosis and MMP7, a previously discovered biomarker for idiopathic pulmonary fibrosis which is categorized as ILD." (PMID 27294886, 2016). "We observed increased expression of WNT5A, cyclin D1, VEGF, and MMP7, all of which are Wnt target gene products that play an important role in pulmonary fibrosis." (PMID 25331176, 2014). "Collagen and other matrix extracellular molecules are the main components of the extracellular matrix, and MMP7 is a key mediator of pulmonary fibrosis." (PMID 25331176, 2014). "MMP7 (also known as matrilysin) is a target gene of the Wnt signaling pathway found on the surface of lung epithelial cells and is a key regulator of pulmonary fibrosis." (PMID 25331176, 2014). "Increased expression of MMP-7 has been observed in airway and alveolar cells at sites of lung cancer, idiopathic pulmonary fibrosis, and cystic fibrosis." (PMID 18007984, 2007). "Matrilysin (MMP-7) was shown to have great importance in idiopathic pulmonary fibrosis and found to be dramatically involved in bleomycin-induced pulmonary fibrosis in mice." (PMID 16504062, 2006). "Metalloproteinase matrilysin (MMP7), a target gene of the canonical Wnt signalling pathway, has recently been identified as a key regulator of pulmonary fibrosis." (PMID 16438732, 2006). "MMP7 regulates processes such as pulmonary fibrosis, lung inflammation, and alveolar epithelial cell adhesion in direct lung injury models because it is constitutively expressed by alveolar epithelial cells and upregulated following direct injury to these cells." (PMID 40341670, 2025). "MMP7 knockout mice have shown resistance to bleomycin induced pulmonary fibrosis." (PMID 39919729, 2025). "Previous reports indicate that MMP7 overexpression induces apoptosis of alveolar epithelial cells and migration of interstitial cells, leading to the destruction of the alveolar wall and the development of pulmonary fibrosis." (PMID 38575860, 2024). "Likewise, MMP7 mediates renal fibrosis via B-catenin signaling, and serum MMP7 is elevated in patients with pulmonary fibrosis." (PMID 38473879, 2024).